NME2 (NME/NM23 nucleoside diphosphate kinase 2)
Diseases named in the same sentence as NME2 in open-access papers (continued):
Sharing a sentence is not in itself a finding about the gene and the disease.
gastric cancer (continued). "Effect of NME2 overexpression on cell cycle of gastric cancer cells*." (PMID 25700270, 2015). "A correlation between NME2 expression and histology grads of gastric carcinomas." (PMID 25700270, 2015). "The results demonstrated that the NME2 knockdown led to cell cycle arrest in G1 phase, while the cell cycle of NME2-rescued cells was similar to that of the wild-type cells, showing that the NME2 silencing suppressed the proliferation of gastric cancer stem-like cells." (PMID 34628473, 2021). "NME2 could be a target for the diagnosis and therapy of gastric cancers." (PMID 34628473, 2021). "NME2 could preserve the stemness of gastric cancer stem-like cells via suppressing their apoptosis." (PMID 34628473, 2021). "In gastric cancer cell lines (HGC-27 and MKN-45), NME2 functions as a master suppressor for apoptosis of gastric cancer by interacting with RNA polymerase II and RNA polymerase II-associated protein 2 (RPAP2)." (PMID 34628473, 2021). "The results of western blot and quantitative real-time PCR showed that the NME2 knockdown significantly downregulated the expression levels of RIPK1, STARD5, and LIMS1 in gastric cancer stem-like cells from human solid tumors." (PMID 34628473, 2021). "Quantitative real-time PCR data indicated that NME2 was significantly upregulated in gastric cancer stem-like cells compared with cancer non-stem-like cells." (PMID 34628473, 2021). "It was found that NME2 was significantly upregulated in gastric cancer stem-like cells compared with gastric cancer non-stem-like cells." (PMID 34628473, 2021). "The data revealed that the DNA, amplified from the gRNA-transfected gastric cancer stem-like cells, was cleaved into two bands by T7E1 enzyme compared with the control, showing that the NME2 gRNA was introduced into the genome of gastric cancer stem-like cells." (PMID 34628473, 2021). "Western blot data demonstrated that the NME2 protein could not be detected in NME2-knockout gastric cancer stem-like cells." (PMID 34628473, 2021).
melanoma (8 papers, 1996 to 2024). A malignant, usually aggressive tumor composed of atypical, neoplastic melanocytes. "To this end, we crossed the HGF/SF and NME1/2+/− mouse strains in a C57BL/6 genetic background to measure the impact of NME1/NME2 deficiency on the metastatic potential of UV-induced melanoma." (PMID 28788083, 2017). "The DNA repair-promoting activity of NME1 and/or NME2 suggests loss of their expression could promote acquisition of mutations that accelerate melanoma progression." (PMID 28788083, 2017). "A decreased level of NME1 and NME2 metastasis suppressor proteins were found in WM793B-resistant primary melanoma, which is possibly the result of vemurafenib-acquired resistance and is one of the causes of increased PI3K/AKT signaling." (PMID 36077308, 2022). "This study demonstrates that the ablation of either Nme1 or Nme2 confers robust increases in metastatic activity in the HGF-based mouse model of UV-induced melanoma." (PMID 33024267, 2021). "Herein, we selectively ablated the tandemly arranged Nme1 and Nme2 genes to assess their individual impacts on metastatic activity in a mouse model (HGF:p16−/−) of ultraviolet radiation (UVR)-induced melanoma." (PMID 33024267, 2021). "In this review, we summarize how the HGF/SF transgenic mouse has been used to reveal metastasis-regulating activity of four different genes (CDK4R24C, survivin and NME1/NME2) in the context of UV-induced melanoma." (PMID 28788083, 2017). "The metastasis-suppressor nme gene (also called nm23), first identified in murine melanoma cells, exists as two forms in human: nme1 and nme2." (PMID 8605098, 1996). "In addition, the PI3K/AKT signaling pathway was shown to be regulated by NME1 and NME2 metastasis suppressors in the WM793B primary melanoma cell line." (PMID 36077308, 2022). "Increased metastatic activity in HPN1 and HPN2 mice was associated with Nme1 or Nme2 inactivation and was not secondary to growth characteristics of melanomas or tumour burden (e.g., size or number)." (PMID 33024267, 2021). "Moreover, mice rendered hemizygous-null at the tandemly-arranged NME1 and NME2 loci (herein designated NME1/2+/−) are highly vulnerable to UV-induced melanoma in situ and epidermal inclusion cyst formation on tail skin, consistent with a deficit in DNA repair." (PMID 28788083, 2017). "In addition, we have observed coordinate downregulation of NME1 and NME2 in human melanoma cell lines of metastatic origin, and this has been reported in human cervical carcinoma specimens as well, suggesting cooperative impacts of NME1 and NME2 on metastatic activity." (PMID 33024267, 2021). "This approach demonstrated robust MSG activity of Nme2 for the first time in any model of spontaneous cancer, while revealing strong suppressor activity of Nme1 in UVR-induced melanoma." (PMID 33024267, 2021). "The study ascribes MSG activity to Nme2 for the first time in an in vivo model of spontaneous cancer, as well as a novel metastasis-suppressor function to Nme1 in the specific context of UVR-induced melanoma." (PMID 33024267, 2021). "Moreover, the HGF/SF model system revealed prototypical MSG activity for NME1 and/or NME2 for the first time in an in vivo setting of melanoma, with suppression of metastasis in the absence of an effect on primary tumor growth." (PMID 28788083, 2017). "Predominant melanomas of HPN2 mice grew at a modestly higher rate than those of HP or HPN1 mice, suggesting Nme2 has a non-canonical suppressive effect on the proliferation of melanoma cells in vivo." (PMID 33024267, 2021).
neuroblastoma (7 papers, 2006 to 2024). Neuroblastoma (NB) is the most common solid, extracranial childhood tumor. "However, NME2 overexpression was also associated with poor prognosis for neuroblastoma and osteosarcoma." (PMID 25700270, 2015). "Neuroblastoma is a pediatric cancer associated with aggressive cases with focal amplification on the arm of chromosome 17q of a region that includes NME1 and NME2 located at 17q23." (PMID 39063217, 2024). "The relative roles of NME1 and NME2 in these hexamers, in the regulation of histidine phosphorylation, and in neuroblastoma pathogenesis remain undefined." (PMID 32392889, 2020). "Products of the NME1 and NME2 genes have been suggested to be the downstream of the c-myc regulatory pathway and involved in the down-regulation of cdc42 function in neuroblastoma." (PMID 25700270, 2015). "Concentration-dependent expression changes were confirmed by qRT-PCR for several N-Myc target genes including NME2, an inhibitor of differentiation located on a region of chromosome 17q that is prone to amplification in aggressive neuroblastomas." (PMID 24009722, 2013). "The specific functional role of NME2 in neuroblastoma, however, remains unknown." (PMID 32392889, 2020). "NME1, NME2, and NME3 were also each identified from the NME1 immunoprecipitated from neuroblastoma cells, which also supports the notion of hetero-oligomerization and the autophosphorylation of these family members." (PMID 32392889, 2020). "We have identified the presence of histidine phosphorylation of a number of proteins, including NME1 and NME2, in neuroblastoma cells and tumors, and have identified potential links between NME1 expression and neuroblastoma cell migration and differentiation." (PMID 32392889, 2020). "Furthermore, in the same paper, the presence of histidine phosphorylation in neuroblastoma cells and tumors was detected on a number of proteins, including NME1 and NME2." (PMID 39063217, 2024). "Furthermore, it has been established that the murine neuroblastoma cell line N1E-115 expressing Nme3 formed significantly fewer colonies in soft agar, while both Nme2-expressing NIH3T3 fibroblasts and Nme2-expressing HLK3 hepatocytes form colonies, unlike control cells that do not form any." (PMID 31877804, 2019).
colon carcinoma (4 papers, 2013 to 2017). "Independently, in oral, breast, and colon cancer, mechanisms of antimetastatic action of NME2 were suggested to be through induction of the epithelial phenotype (mesenchymal to epithelial transition)." (PMID 28717007, 2017). "Regarding colon cancer network, genes including NME2, ATP1A1, CD24 and IFI6 showed the most connectivity." (PMID 29118934, 2017). "The expression of NME2 was found to be reduced in different cancers including colon cancer." (PMID 29118934, 2017).
leukemia (3 papers, 2011 to 2024). A malignant (clonal) hematologic disorder, involving hematopoietic stem cells and characterized by the presence of primitive or atypical myeloid or lymphoid cells in the bone marrow and the blood. "There were many leukemia-related genes in the up-regulated genes of K1 group, such as UBB (P=1.56e-50), MIF (P=2.76e-50), DRAP1 (P=1.72e-49), RPS25 (P=1.9e-49), EIF3K (P=4.77e-49), SSNA1 (P=1.27e-48), GPX4 (P=3.01e-48), PHB2 (P=7.13e-48), NME2 (P=2.44e-47) or CFL1 (P=4.07e-47)." (PMID 36408189, 2022).
lung adenocarcinoma (3 papers, 2014 to 2019). A carcinoma that arises from the lung and is characterized by the presence of malignant glandular epithelial cells. "First, in order to understand whether lung adenocarcinoma-derived A549 cells represent a possible model for molecular studies, we probed the transcriptome of A549 cells following NME2 depletion and assessed its correlation with the gene expression profile of patient-derived lung tumors." (PMID 25249619, 2014).
osteosarcoma (3 papers, 2017 to 2025). A usually aggressive malignant bone-forming mesenchymal neoplasm, predominantly affecting adolescents and young adults. "Overexpression of the NME2 protein can notably stimulate the proliferation of osteosarcoma cell lines." (PMID 41476960, 2025). "Mechanistically, NME2 can regulate c-Myc expression, promoting tumor cell proliferation in osteosarcoma cells, Hela cells, and HepG2 cells." (PMID 39063217, 2024). "Some studies have demonstrated that NME2 negatively regulates migration and invasion in cancer, such as BCa, osteosarcoma, gastric, and non-small cell lung cancers." (PMID 39063217, 2024). "For instance, in osteosarcoma, the level of miR-645 was increased in tumor tissue as compared to normal tissue and could promote cell migration by inhibiting NME2 translation through direct binding to its 3′ untranslated region." (PMID 39063217, 2024).
ovarian carcinoma (3 papers, 1995 to 2016). A malignant neoplasm originating from the surface ovarian epithelium. "Multiple molecules have previously been identified to interact or regulate NME2, such as EGFR, c-erbB-2, c-erbB-3 and sex steroid receptor in ovarian carcinomas." (PMID 25700270, 2015).
renal carcinoma (3 papers, 2015 to 2024). A carcinoma arising from the epithelium of the renal parenchyma or the renal pelvis. "NME2 was also found to interact with MDM2 (Mouse double minute 2 homolog) to reduce the motility of renal carcinoma cells." (PMID 25700270, 2015). "Most of the genes have usually been investigated as prognostic biomarkers in renal cancer, and RPS18, RPL30, NME2, and RPS25 usually have been investigated as unfavorable predictors, while GAB2 has been reported as favorable predictor in renal cancer." (PMID 34208938, 2021).
bipolar disorder (2 papers, 2021 to 2025). A disorder of the brain that causes unusual shifts in mood, energy, activity levels and the ability to carry out day-to-day tasks. "Although no previous literature has directly linked NME2 to bipolar disorder, our findings suggest its potential role at the protein level in the disease pathogenesis." (PMID 40427743, 2025). "Another gene, NME2, was found to be significantly associated with bipolar disorder based on protein-based fine-mapping (p = 8.6 × 10−6) but not by RNA-based fine-mapping (p = 1)." (PMID 40427743, 2025). "Also, only CEWAS found FAHD2B, HDAC5, MBTD1, NME2, and XPNPEP3 for bipolar disorder." (PMID 34807913, 2021).
breast tumor (2 papers, 2021 to 2022). "Moreover, we explore the role of both NME1 and NME2 in such metastasis-associated biological processes as EMT, migration, and invasion by using a breast tumor cell line model." (PMID 36111347, 2022). "Collectively, these data indicated that the loss of NME1, but not of NME2, accelerated the invasive switch of breast tumors in the intraductal xenograft assay, possibly in relation with increased plasma membrane MT1-MMP levels." (PMID 34012098, 2021). "Here, we investigated the expression of NME1 and NME2 in synchronous DCIS and IBC foci in breast tumors." (PMID 34012098, 2021).
colorectal cancer (2 papers, 2024). A primary or metastatic malignant neoplasm that affects the colon or rectum. "Depletion of NME2 in HCC, colorectal carcinoma, or breast cancer cell lines has no impact on invasion or migration." (PMID 39063217, 2024).
colorectal tumour (2 papers, 1995 to 2019). "Kaplan Meier survival curve showed the expression of HLAB, 14-3-3β, ADAMTS2, LTBP3, NME2 and JAG2 on colorectal tumour cells associated with CRC specific survival." (PMID 30679934, 2019). "A number of known or putative tumour-suppressor genes including NF1, BRCA1, NME1, NME2 and prohibitin are present on the long arm of chromosome 17, and this region has not been extensively analysed in colorectal tumours." (PMID 7734302, 1995).
ductal breast carcinoma in situ (2 papers, 2022 to 2023). A carcinoma entirely confined to the mammary ducts. "By contrast, NME2 was upregulated in ductal carcinoma in situ, but remained highly expressed in invasive tumors supporting the conclusion that NME2 is not a repressor of invasion." (PMID 37353690, 2023). "For this, we compared three different cell lines: ductal breast carcinoma in situ that are considered control tumor cells and two derivative cell lines obtained by inactivation of either NME1 or its closely related isoform NME2." (PMID 36111347, 2022).
prostate carcinoma (2 papers, 2024). A carcinoma that arises from epithelial cells of the prostate gland. "In prostate cancer, NME2 acts as an upstream regulator of MYC, and their increased activity is associated with a risk of resistance to enzalutamide, a treatment in prostate cancer." (PMID 39063217, 2024). "A few studies demonstrated that NME2 plays a role in resistance to treatment in colorectal cancer and prostate cancer." (PMID 39063217, 2024).
adenocarcinoma of the prostate (1 paper, 2020). "However, several reports on increased NME2 gene expression have also been reported in adenocarcinoma of the prostate, solid tumors and stroke." (PMID 32366041, 2020).
anemia (1 paper, 2020). A reduction in the number of red blood cells, the amount of hemoglobin, and/or the volume of packed red blood cells. "NME2 promotes the development of erythropoiesis, because the iron transport receptor TfR1 in the red blood cells of Nme1/Nme2-deficient mice is down-regulated, characterized by hypoplasia, severe anemia, and perinatal death." (PMID 33281799, 2020).
Cerebral ischemia (1 paper, 2025). Restriction of arterial blood supply to the brain associated with insufficient oxygenation to support the metabolic requirements of the tissue. "Furthermore, our findings revealed additional proteins that may serve as biomarkers for cerebral ischemia-reperfusion injury, including STAT3, NME2, VCL, and CCT3." (PMID 39936033, 2025).
deafness (1 paper, 2019). An inherited or acquired condition characterized by the complete loss of the ability to hear from one or both ears. "Although a subset of genes that related to IHC machinery and deafness were found to be differentially expressed, a gradient of gene expression was indeed detected in Ocm, Pvalb, Prkd1, Fbxo32, Nme2, and Sncg, which may play putative roles in the Ca2+ buffering and survival regulation." (PMID 32038162, 2019).
glioma (1 paper, 2020). A benign or malignant brain and spinal cord tumor that arises from glial cells (astrocytes, oligodendrocytes, ependymal cells). "CNTN1 was identified as a TAA along with other four TAAs (CRKII, CFL1, NME2, and TKT) in IDTH1-mutant lower grade gliomas through a proteomic and immunologic approach." (PMID 32752094, 2020).
invasive breast carcinoma (1 paper, 2022). A carcinoma that infiltrates the breast parenchyma. "As a model, we used human invasive breast carcinoma cells overexpressing NME1 or NME2, and first analysed in detail the presence of both isoforms in EV subtypes by capillary Western immunoassay (WES) and immunoelectron microscopy." (PMID 36010906, 2022).
liver disease (1 paper, 2024). "By training random forest models, a biomarker panel comprising KNG1, F11, KLKB1, CAPNS1, CDH1, CPN2, NME2, was identified by feature selection for liver disease detection." (PMID 39207047, 2024).
liver fibrosis (1 paper, 2022). "NME2 is a histidine kinase involved in TGF-β–induced activation of hepatic stellate cells, a liver pericyte prototype, and CCl4-induced liver fibrosis, and Gas5 is a long noncoding RNA whose high levels are associated with liver fibrosis." (PMID 36136606, 2022).
mesothelioma (1 paper, 2009). A usually malignant and aggressive neoplasm of the mesothelium which is often associated with exposure to asbestos. "The local invasive, non-metastatic phenotype of mesothelioma, could partly be due to overexpression of the known metastasis suppressors NME1 and NME2." (PMID 19662092, 2009).
metastatic tumors (1 paper, 2023). "Moreover, analysis of gene expression datasets from breast, colon, lung and ovarian tumors revealed that there is significantly less NME2 expression in metastatic tumors than in non-metastatic tumors." (PMID 37353690, 2023).
pneumonia (1 paper, 2019). An acute, acute and chronic, or chronic inflammation focally or diffusely affecting the lung parenchyma, caused by an infection in one or both of the lungs (by bacteria, viruses, fungi, or mycoplasma.). "Glyceraldehyde 3‐phosphate dehydrogenase (GAPDH; degree = 13, closeness centrality = 0.54), Nucleoside diphosphate kinase B (NME2; degree = 6, closeness centrality = 0.44) and Cofilin‐1 (CFL1; degree = 6, closeness centrality = 0.42) were the three hub proteins of the pneumonia‐specific PPI network." (PMID 30761252, 2019).
renal cell carcinoma (1 paper, 2024). "One study demonstrated that in renal cell carcinoma, MDM2 is able to interact with NME2 and potentially promote the ubiquitylation of NME2 independently of its protein kinase activity; therefore, NME2 is not able to negatively regulate cell migration." (PMID 39063217, 2024).
situ carcinoma (1 paper, 2022). "Here we studied one of its derivatives, the in situ carcinoma cells, MCF10DCIS.com, in which NME1 or NME2 were ablated." (PMID 36111347, 2022).
tongue squamous cell carcinoma (1 paper, 2015). A squamous cell carcinoma that arises from the tongue. "Plakoglobin was reported to interact with NME2 to promote its expression in cells from human tongue squamous cell carcinoma." (PMID 25700270, 2015).
triple-negative breast carcinoma (1 paper, 2018). An invasive breast carcinoma which is negative for expression of estrogen receptor (ER), progesterone receptor (PR), and human epidermal growth factor receptor 2 (HER2). "MDA-MB-231T triple-negative breast cancer cells were transfected with Flag-tagged human NME1, NME2, murine Nme1 or an empty vector (V), and pools of Flag-positive cells were collected." (PMID 29535799, 2018).